VIM (vimentin)
Diseases named in the same sentence as VIM in open-access papers (continued):
Sharing a sentence is not in itself a finding about the gene and the disease.
prostate carcinoma (continued). "SSX2 knockdown, in the 22Rv1 prostate cancer line, demonstrated a large fold change in many different EMT associated genes (TWIST1, ZEB2, MMP2, VIM, CDH1, CDH2) however these genes did not respond in an anticipated or canonical way." (PMID 27276714, 2016). "Moreover, the expression of E-cadherin (an epithelial marker) was downregulated along with upregulation of Vimentin (a mesenchymal marker), indicating the involvement of MTA1 in epithelial-to-mesenchymal transition (EMT) of prostate cancer cells." (PMID 26943043, 2016). "Immunofluorescent double stainings confirmed that co-expression of mesenchymal markers was uncommon, as we found no prostate cancer cells that co-expressed N-cadherin with fibronectin and only rare (<1%) cells that co-expressed N-cadherin with vimentin." (PMID 26041890, 2015). "CK-positive/Vimentin-positive/CD45-negative, and CK-negative/Vimentin-positive/CD45-negative cells were also observed in four of five prostate cancer patients but rarely in three healthy controls, indicating that Parsortix harvests CTCs with both epithelial and mesenchymal features." (PMID 26397728, 2015). "Indeed, PC3 and DU-145 prostate cancer cells overexpressing SULF2 exhibited increased levels of CD44, vimentin, and N-cadherin." (PMID 25887999, 2015). "Thus, prostate cancer cells were immunostained for CD44, vimentin, and N-cadherin and the presence as well as their quantity analyzed by flow cytometry." (PMID 25887999, 2015). "Levels of increased vimentin and decreased E-cadherin were correlated with the L1CAM knockdown effectiveness of shRNA, revealing an undescribed mechanism of the L1CAM on prostate cancer metastasis that contradicts its known function of promoting the EMT seen in other cancer types." (PMID 25294816, 2014). "Interestingly, 6 weeks after maintaining the prostate cancer cells in stromal cell media, the prostate cancer cells underwent EMT, which was biochemically defined by decreased E-cadherin and increased vimentin mRNA expression." (PMID 25566500, 2014). "An additional possible benefit for targeting through vimentin recognition is that a unique extracellular deposition for vimentin has now been shown to mark the stroma of prostate cancer lesions but not prostate hyperplasia or normal prostate epithelial tissue." (PMID 24212937, 2011). "We found that unlike the metastatic prostate cancer lines, no surface vimentin is detectable on HMEC-1 cells." (PMID 24212937, 2011). "Classic regulators of epithelial‐mesenchymal transition (EMT), such as TWIST1, vimentin or N‐cadherin, have also been identified as ETV1 target genes involved in cell invasion induced by this transcription factor particularly in colorectal and prostate cancers." (PMID 40275610, 2025). "However, reports on TWIST1/Vimentin methylation in urothelial carcinomas of the upper urinary tract or prostate cancer are almost non-existent." (PMID 38575639, 2024). "Additionally, regardless of prostate cancer stage, the combination of EpCAM and vimentin antibodies proved to be more effective in isolating CTCs than using either EpCAM or vimentin antibodies alone." (PMID 37345161, 2023). "In a study on prostate cancer, it was proven that CAPE treatment suppresses the migration and invasion of PC-3 and DU-145 PCa cells via the elevation of ROR2 (tyrosine-kinase-like orphan receptor 2) and E-cadherin proteins and via the reduction in vimentin protein." (PMID 37570782, 2023). "However, vimentin expression may also be high in other cells of mesenchymal origin (e.g., mesenchymal stem cells and fibrocytes), and is a surrogate marker for EMT in prostate cancer." (PMID 36671452, 2022). "Silibinin, a flavanone isolated from milk thistle, decreased vimentin protein expression in a dose- and time-dependent manner and suppressed MMP-2 expression, while it regulated cytokeratin-18 gene in ARCaPM cells, an in vitro model of prostate cancer progression to bone metastasis." (PMID 34572548, 2021).
prostate carcinoma (continued). "Marine, a herbal medicine derived from Sophora flavescens, induces anti-prostate cancer effects by activating GRP78, CHOP, and ATF4, phosphorylating eIF2α, and inhibiting the EMT process via the decrease of E-cadherin and the increase of N-cadherin and vimentin." (PMID 34830138, 2021). "In agreement with what was found in the in vitro studies, protein levels of mesenchymal markers N-Cadherin and Vimentin were higher in PC3 miR-214KO tumors versus WT tumors, whereas protein levels of E-Cadherin were lower, which was consistent with increased EMT in PC3 prostate cancer cells." (PMID 34884984, 2021). "In the meantime, the results showed that hypoxia-induced EMT in androgen-independent prostate cancer cells along with increased TRPM7 expression, showing as hypoxia-induced significant decrease of E-cadherin (E-Cad) while an induced increase of expression of vimentin and N-cadherin (N-Cad)." (PMID 32215176, 2020). "Furthermore, the genomic inhibition of ESRP1/2 in prostate cancer cells did not affect the expression of E-cadherin and vimentin, key genes involved in EMT." (PMID 32820253, 2020). "Furthermore, knockdown of CNTN1 in prostate cancer cell lines also inhibited the PI3K/AKT pathway and suppressed the EMT process via concomitant upregulation of E−cadherin and downregulation of N-cadherin and vimentin." (PMID 33194679, 2020). "In addition, E-cadherin expression was increased and vimentin expression was decreased after propofol treatment as compared with the hypoxia-induced group, indicating that propofol can reverse hypoxia-induced EMT in prostate cancer cells." (PMID 29568752, 2018). "Interestingly, our findings showed that down regulation of NR6A1 protein expression significantly increased E-cadherin expression, and markedly reduced N-cadherin, Vimentin and ZEB-1 expression in prostate cancer cells (DU145 and PC3), while overexpression of NR6A1 hold the opposite effects." (PMID 28969082, 2017). "RANKL-activation of RANK increased expression of vimentin, N-cadherin, Snail, and Twist, decreased the expression of E-cadherin and drove EMT in normal breast acinar cells and a number of cancers including breast cancer, hepatocellular carcinoma, endometrial, lung and prostate cancer." (PMID 28977822, 2017). "Taken together, these data demonstrate that WA targets vimentin and promotes cell death in prostate cancer cells, but not in normal fibroblasts, through increased c-Fos level, reduced FLIP level, and/or enhanced ROS generation probably via WA-mediated disruption of the cytoskeletal architecture." (PMID 26230090, 2015). "During EMT of prostate cancer cells, the expression of transcription factors such as Snail, Slug, Twist, E47, ZEB1, and ZEB2 is increased, which leads to increased expression of N-cadherin and vimentin and concomitantly decreased expression of E-cadherin and cytokeratins." (PMID 23785446, 2013). "A recent study of isogenic prostate cancer cell lines using an 8-Plex ITRAQ comparative quantitative proteome analysis demonstrated the lack of vimentin expression in the androgen responsive LNCaP cells and almost identical expression levels in the androgen-independent PC-3 cells." (PMID 23717685, 2013). "CTCs present in CTC clusters always appeared to be large, and any small cells observed in these clusters were not positive for any of our markers (VIM, KRT, SERPINE1, PSA) and are thus unlikely to be prostate cancer cells." (PMID 34206049, 2021). "With regard to prostate cancer targeting, we were able to show uptake of CPMV nanoparticles by the prostate cancer cell lines and that HMEC-1 cells (surrogate cells for human vascular endothelium) did not bind the SC5 vimentin specific mAb." (PMID 24212937, 2011). "Therefore, miR-203 probably inhibits prostate cancer metastasis in vivo by IRS-1-mediated the down-regulation of Slug rather than the EMT classical proteins like E-cadherin and Vimentin." (PMID 33109107, 2020).
colorectal cancer (205 papers, 2007 to 2026). A primary or metastatic malignant neoplasm that affects the colon or rectum. "Vimentin is strongly and positively expressed in endometrial, ovarian, and colorectal cancers 28-30, providing diagnostic and therapeutic insights." (PMID 39895792, 2025). "Higher levels of vimentin in breast, lung, and colorectal cancers are associated with severe metastasis and poor outcome." (PMID 36517670, 2023). "For example, its intrinsic expression in colorectal cancer cell lines decreased E-cadherin expression and increased stem cell-associated markers such as N-cadherin, vimentin, CD133, CD44, and OCT4." (PMID 36901916, 2023). "A previous study has suggested that positive vimentin immunostaining is associated with high-grade colorectal cancer." (PMID 37749564, 2023). "In colorectal cancer, altered expression of E-cadherin and β-catenin and progressive increase of vimentin in late stages are associated significantly with aggressive tumor cell behavior and, furthermore, confer resistance to cancer drugs." (PMID 31455041, 2019). "Silencing of VIM by promoter methylation has been linked to poor prognosis in colorectal cancer using qMSP to detect serum methylation level in several studies." (PMID 29038612, 2017). "Since Vimentin upregulation is associated with poor prognosis and lower survival in prostate and colorectal cancer types, it is clinically relevant that LSD1 upregulates Vimentin during the EMT in HPV16 E7-induced cervical cancer." (PMID 27894088, 2017). "A previous study suggested that vimentin methylation was associated with liver metastasis and peritoneal dissemination in colorectal cancer." (PMID 24555885, 2014). "Vimentin is known for its effects on colorectal cancer proliferation, invasion, and migration, and vimentin expression is associated with higher tumor grade, metastasis, and shorter survival in colorectal cancer." (PMID 38612832, 2024). "In addition, applying HEART on two subpopulations of megakaryocytes, we found several potential cancer biomarkers (CTTN, S100A4, S100A6, UBA52, FAU, and VIM, etc.)associated with colorectal cancer progression and metastasis in literature." (PMID 36523772, 2022). "Furthermore, AIM2 played an protumor role in colorectal tumors because overexpression of AIM2 in colorectal cancer cells induced the expression of invasion‐associated genes such as VIM and MCAM." (PMID 35070978, 2021). "Recently, it is reported that PPM1H knockdown in colorectal cancer cells can induce vimentin expression and activate cancer-associated fibroblasts (CAFs), which in turn can promote the proliferation and migration of colorectal cancer cell with low PPM1H expression." (PMID 33125346, 2020). "High expression of PLEC is associated with poor prognosis in breast and colorectal cancer and was reported to drive cancer metastasis, by stabilizing invadopodia via anchoring to vimentin intermediate filament scaffolds, a necessary process in cancer cell invasion and extravasation." (PMID 33330445, 2020). "Colorectal cancer diagnostic assays of methylated sequences of either the SEPT9 or VIM genes are now commercially available for detection in plasma and stool samples respectively and other genes such as THBSI and SDC2 are also being evaluated for plasma-based diagnosis." (PMID 24485021, 2014). "Indeed, the presence of neuropilin-2 in colorectal carcinoma cell lines was correlated with loss of epithelial markers such as cytokeratin-20 and E-cadherin and with acquisition of mesenchymal molecules such as vimentin." (PMID 21747928, 2011). "Some double Cytokeratin+/Vimentin+ cells were also found, similar to colorectal cancer, suggesting the presence of epithelial‐to‐mesenchymal transition (EMT) subpopulations." (PMID 41144934, 2026). "Downregulating TFAM in colorectal cancer can also downregulate E-cadherin, vimentin, and snail proteins." (PMID 39927160, 2025).
colorectal cancer (continued). "Salinomycin, an ionophore antibiotic, has also shown promise, as it downregulated vimentin, upregulated E‐cadherin in colorectal cancer cells, reversed doxorubicin‐induced EMT, and restored chemosensitivity in vitro and in vivo." (PMID 40443053, 2025). "In an organoid co-culture model of colorectal cancer, an upregulation in the phosphorylation level of VIM is considered a marker of epithelial–mesenchymal transition (EMT) and is associated with the invasive phenotype induced by stromal cells." (PMID 41153737, 2025). "DHA has been shown to suppress expression of EMT-related genes including SNAIL, SLUG, ZEB1, and ZEB2 in colorectal cancer cells, resulting in decreased expression of N-cadherin and vimentin, increased E-cadherin expression, and reduced cell migration." (PMID 41009329, 2025). "In this study, we report that transmembrane 9 superfamily member 1 (TM9SF1) suppresses colorectal cancer metastasis via selective autophagic degradation of Vimentin." (PMID 40175707, 2025). "One study identified mRNA expression of EMT-related cell markers including E-cadherin and Vimentin in commonly used human colorectal cancer cell lines." (PMID 38762631, 2024). "When TFF3 is overexpressed in colorectal cancer cells, transcription factors such Twist1, Snail, and Vimentin are expressed more often while E-cadherin levels are concurrently decreased." (PMID 39839775, 2024). "An increase in vimentin expression would be an indication that CB1 agonists enhance the metastatic progression of the SW-620 colorectal cancer cells." (PMID 38534324, 2024). "In colorectal cancer, Vimentin-positive circulating tumor cells have been shown to be a prognostic biomarker for the advanced stages of the disease." (PMID 39766136, 2024). "ONECUT2 has been implicated in the regulation of epithelial-mesenchymal transition (in colorectal cancer) by controlling the expression of E-cadherin and vimentin, thereby enhancing colorectal cancer cell invasiveness and metastatic potential." (PMID 38997271, 2024). "The expressions of epithelial marker E-cadherin and mesenchymal marker Vimentin were analyzed in tumor tissue of 106 patients with colorectal cancer diagnosed before the age of 45 years." (PMID 39061649, 2024). "In this study, it was experimentally confirmed that C5aR1 in CRC cell lines regulates the expression of EMT-related markers E-cadherin and Vimentin, thus affecting the invasion and migration of colorectal cancer cells." (PMID 36192575, 2023). "For example, in the United States, hypermethylation in the promoter regions of BMP3, NDRG4, SEPT9, and VIM genes have been approved for colorectal cancer screening." (PMID 36831050, 2023). "Evidences support role of Vimentin over-expression in stimulating metastasis and invasion in colorectal cancer." (PMID 35642021, 2022). "circPTK2 promoted EMT of colorectal cancer cells by up-regulating vimentin expression via physically binding to vimentin." (PMID 35538537, 2022). "Another study demonstrated that cotreatment of 5-FU and resveratrol can inhibit the EMT pathway and down-regulate vimentin expression in colorectal cancer cells." (PMID 35449812, 2022). "To investigate the mechanism of HMGB3 knockdown-mediated colorectal cancer inhibition, we detected a downregulation of N-cadherin, Vimentin and β-catenin proteins after knockdown of HMGB3." (PMID 35712661, 2022). "Meanwhile, the upregulation of miR-6511b-5p increased E-cadherin and β-catenin expression and decreased vimentin and N-cadherin expression in colorectal cancer cells." (PMID 35590122, 2022). "The vimentin gene is frequently methylated in advanced colorectal cancer cells, allowing methylation of the gene to be used as a diagnostic tool for diagnosis of late-stage colorectal cancer." (PMID 36230521, 2022).
colorectal cancer (continued). "When neuropilin-2 was found in colorectal cancer cell lines, researchers discovered that epithelial markers like cytokeratin-20 and E-cadherin were lost and mesenchymal molecules like vimentin were acquired." (PMID 35052853, 2022). "Then, we examined the expression levels of AGO2, E-cadherin, and vimentin in 284 colorectal cancer tissue samples." (PMID 33846300, 2021). "CircPTK2 up-regulated in colorectal cancer tissues can promote EMT process of colorectal cancer cells in vitro and in vivo by binding to vimentin at Ser38, Ser55, and Ser82 sites." (PMID 33430866, 2021). "For example, miR-17-5p expression has been shown to decrease in primary CRC tissues; overexpression of miR-17-5p significantly represses cell migration and invasion by modulating vimentin expression in colorectal cancer." (PMID 34858987, 2021). "Recently, circPTK2 was also associated with tumor growth and metastasis in colorectal cancer (CRC) and promoted EMT of CRC cells in vitro and in vivo by binding to vimentin protein on sites Ser38, Ser55 and Ser8235." (PMID 34326381, 2021). "Vimentin, only identified in ovarian cancer cells; growth factor receptor-bound protein 2, only identified in colorectal cancer cells; and glutathione-S-transferase π, identified in all four cell lines, were further investigated." (PMID 32466394, 2020). "The overexpression of vimentin in colorectal cancer is related to stromal components, microvascular-lined endothelial cells, and tumor-infiltrating lymphocytes." (PMID 32670437, 2020). "In summary, we reported that increased expression levels of hsa_circ_0005273, spliced from the pre-mRNA PTK2, was involved in the metastasis of colorectal cancer via physical binding to phosphorylation sites Ser38, Ser55 and Ser82 of vimentin." (PMID 31973707, 2020). "In conclusion, this study showed that the combination of the CFEF and cetuximab is able to inhibit proliferation by reducing K-Ras and vimentin expression in colorectal cancer in vivo." (PMID 32765634, 2020). "We investigated the level of Vimentin and E-cadherin expression in relation to invasion and metastasis on colorectal cancer patients." (PMID 32665775, 2020). "The aberrant methylation of Vimentin in feces is the basis of a commercial test for colorectal cancer." (PMID 32206039, 2020). "FAK inhibitors can also inhibit the downregulation of E-cadherin and upregulation of vimentin in the process of EGF-induced EMT in colorectal cancer cells." (PMID 32148496, 2020). "Overall, according to our study Vimentin as a mesenchymal marker accelerates and E-cadherin as a structural adhesion protein reduces in colorectal cancer." (PMID 32665775, 2020). "Immunohistochemical staining was used to detect the macrophages infiltration (CD68 and CD163), epithelial–mesenchymal transition (EMT) markers (E-cadherin and Vimentin) expression in serial sections of human colorectal cancer (CRC) specimens." (PMID 30927925, 2019). "In colorectal cancer, the lncRNA H19 was reported to derepress the endogenous genes, Vimentin, ZEB1, and ZEB2, by targeting miR138 and miR200a." (PMID 31752684, 2019). "Another study in colorectal cancer showed that Plk1‐mediated invasion occurs via phosphorylation of vimentin (Ser82), which in turn regulates the cell surface levels of β‐integrin, a key player in cell adhesion." (PMID 30859681, 2019). "Transcriptomic analysis of mutant and wild-type β-catenin colorectal cancer cells showed that mutant cells were enriched with mesenchymal markers such as Vimentin (VIM) and that ELF3 was significantly more abundant in wild-type β-catenin cells." (PMID 30148686, 2019). "Previous study has reported that FSTL1 binds to VIM and facilitates colorectal cancer metastasis through activating the focal adhesion signalling pathway." (PMID 31772671, 2019). "Its overexpression enhanced invasion and metastasis of colorectal carcinoma by the downregulation of E-cadherin and by increasing N-cadherin and vimentin expression." (PMID 31191685, 2019).